IL6 (interleukin 6)
Diseases named in the same sentence as IL6 in open-access papers (continued):
Sharing a sentence is not in itself a finding about the gene and the disease.
pneumonia (continued). "IL-6 is an important predictor for evaluating the severity of severe pneumonia and treatment failure and has been widely studied in clinical practice." (PMID 39411281, 2024). "In our study, we found a correlation between POD after femoral neck surgery and high levels of postoperative IL-6 and leucocytes as well as the occurrence of pneumonia." (PMID 39112758, 2024). "The primary objective of this study is to evaluate the predictive value of PedPne in comparison with inflammatory biomarkers (IL-6 and dNLR) for the development of pneumonia in pediatric patients following SARS-CoV-2 infection." (PMID 39202577, 2024). "Lung tumor necrosis factor-α, interleukin (IL)-1β, IL-6, and IL-10 were significantly decreased at 48 hours after pneumonia induction in the exercise group compared with the control group." (PMID 38193770, 2024). "The findings of this study introduce novel insights into the clinical utility of combining PedPne with inflammatory biomarkers such as dNLR and IL-6 for diagnosing and managing pneumonia in pediatric patients post-SARS-CoV-2 infection." (PMID 39202577, 2024). "In our study, we performed a correlation analysis in the group of patients with HIV and pneumonia, evaluating the cytokines IL-6, IL-17A, MCP1/CCL2, PAI1, IL-1β, and VEGF/VPF in relation to key parameters of lung function." (PMID 38251391, 2024). "In a post-viral bacterial infection-induced pneumonia mouse model, BBD increased the survival rate which was associated with significantly reduced serum IL-6 levels." (PMID 39051370, 2024). "Patients with HIV and pneumonia presented elevated levels of cytokines and chemokines (IL-6, IL-8, IL-18, IL-1RA, IL-10, IP-10, MCP-1, and MIP-1β) compared to those with only HIV." (PMID 38251391, 2024). "Given the current research status, we believe that dynamic detection of CRP, PCT, blood routine, IL-6, and SAA in high-risk children is helpful for assessing the severity of pneumonia." (PMID 39411281, 2024). "Studies have reported that an IL-6 to IL-10 ratio greater than five predicts the occurrence of severe pneumonia in children." (PMID 39411281, 2024). "Studies have demonstrated a strong association between IL-6 levels and several clinical severity scores, including MEWS, CURB 65, and the pneumonia severity index (PSI)." (PMID 39727640, 2024). "In acute pneumonia, the activation of neutrophils, which act as first responders, results in the release of autocrine cytokines and chemokines such as IL-8, IL-4, IL-6, IL-10, IL-1β, transforming growth factor (TGF)-β, and TNF-α, among others." (PMID 38251391, 2024). "It was estimated that CRP mediated 32.59% (95% CI: 17.90%, 47.27%) of the effect of BMI on pneumonia, which was higher than the proportion mediated by IL-6 (7.96% [95% CI: 1.79%, 14.14%]) and FEV1 (4.04% [95% CI: 0.34%, 7.74%])." (PMID 39337223, 2024). "After removing the next factor, namely, IL-6, statistically significant results were gender (β = −0.27), pneumonia (β = 0.357), and IL-10 (β = −0.21)." (PMID 39335569, 2024). "Both pneumonia and GI sepsis trigger a robust systemic inflammatory response characterized by the release of pro-inflammatory cytokines such as interleukin-6 (IL-6) and tumor necrosis factor-alpha (TNF-α)." (PMID 39258039, 2024). "The DCA–VPA treatment of T lymphocytes from male SARS-CoV-2-infected patients with pneumonia was probably most effective in suppressing the expression of the IL6 gene, a key cytokine of the infection." (PMID 38543303, 2024). "This study delineated the prognostic utility of Pediatric Pneumonia Ultrasound Scores (PedPne) and specific inflammatory biomarkers like dNLR and IL-6 in pediatric patients developing pneumonia post-SARS-CoV-2 infection." (PMID 39202577, 2024). "First, patients with HIV and pneumonia exhibited elevated plasma levels of various cytokines, including IL-6, IL-8, IL-18, IL-1RA, IL-10, IP-10, MCP-1, and MIP-1β, compared to patients with HIV alone." (PMID 38251391, 2024).
pneumonia (continued). "Regression analysis further substantiated the predictive strength of these biomarkers, with IL-6 showing substantial hazard ratios, indicating a significant increase in the likelihood of pneumonia development as these marker levels rise." (PMID 39202577, 2024). "To determine if inflammation influenced the risk of incident pneumonia in CHIP carriers, we added an interaction term for a common SNPs in the IL6 receptor gene (IL6R [rs2228415]), which reduces IL6 signaling." (PMID 38573824, 2024). "Spearman’s analysis revealed a significant positive correlation between pneumonia and neutrophile, interleukin-6 IL-6, C-reactive protein CRP (p = 0.01, p < 0.001, p < 0.001), negative to lymphocyte count (p < 0.001)." (PMID 37608339, 2023). "Blood testing showed rapid decreases in the levels of CRP and IL-6, and imaging tests showed the resolution of pneumonia." (PMID 37124420, 2023). "Macrolides have been shown to regulate cytokines such as tumor necrosis factor α, interleukin 1, interleukin 6, interleukin 8 and interferon γ, which play an important role in host defense mechanisms in patients with pneumonia." (PMID 36910529, 2023). "faecalis causes pneumonia in mice due to the activation of ILC-2 and CD8+ T cells, which, in turn, produce large amounts of proinflammatory IL-17 and IL-6 in the lungs." (PMID 36624474, 2023). "Keywords related to ALI, such as nitric oxide synthase, pneumonia, and interleukin-6, began to burst at an early stage." (PMID 37398906, 2023). "As the first inflammatory factors in pneumonia, interleukin 6 and 10 can rapidly respond to inflammatory recruitment and mediate immune Cell migration." (PMID 37764047, 2023). "Interleukin-6 and interleukin-17 can produce large amounts of inflammatory factors and thus promote the development of pneumonia." (PMID 36624474, 2023). "In baseline evaluation, Omicron pneumonia patients with high levels of IL-6, low levels of oxygen saturation, and greater CT lung infiltration should be monitored closely to minimize the risk of progression to severe conditions/poor outcomes." (PMID 37305146, 2023). "The levels of IL-6, procalcitonin, sRAGE, and angiopoietin-2 were lower post-event compared to the day of pneumonia diagnosis, while syndecan-1 and angiopoietin-1 concentrations were higher post-event; the other host response biomarkers remained unaltered." (PMID 37415223, 2023). "Among these, LBP, IL-6, and IL-2R are features for CAP diagnosis, and the combination of LBP, sFas, TRAIL, IL-6, and IL-8 allowed discrimination between uncomplicated and severe forms of pneumonia." (PMID 37342494, 2023). "Among the possible effects of the disease, the levels of PO2/FiO2 resulted in being significantly lower in the pneumonia group, while IL-6, CRP, rate of admission to ICU, and death were higher among the patients with pneumonia." (PMID 37631910, 2023). "With regard to cytokine release and systemic inflammation IL-1RA, tenascin-C, and sCD163 increased from baseline to the day of pneumonia diagnosis, IL-6, IL-10, procalcitonin and sRAGE decreased, and IL-8, MMP-8, and sTREM-1 remained unchanged in cases." (PMID 37415223, 2023). "IL-6 levels are also a marker for the development of COVID-19-related pneumonia and respiratory failure, and a prognosticator for the survival rate." (PMID 36987476, 2023). "At pneumonia diagnosis, plasma IL-6 was higher in the pneumonia-with-VILI group (579.94 ± 138.79 vs. 356.79 ± 233.66 pg/mL, p = 0.038)." (PMID 37328874, 2023). "Consistent with LPS-treated mice, serum and BALF IL-1β and IL-6 levels in pneumonia patients were higher than in controls." (PMID 36923935, 2023). "Overall, pneumonia-derived CVB4 caused significant increases in two important pro-inflammatory factors, IL-6 and IL-1b, on both sides in the early stages of infection." (PMID 37725516, 2023).
pneumonia (continued). "The highest burden of P. aeruginosa was found at pneumonia diagnosis in all animals, as well as a high inflammatory response shown by a release of interleukin (IL)-6 and IL-8." (PMID 37328874, 2023). "The group with pneumonia-related bacteremia exhibited higher rates of CKD, CRP, PCT, IL-6 levels, and infection rates with other bacteria than the pneumonia-only group, while PA levels were lower (all p ≤ 0.05)." (PMID 37768395, 2023). "Blood testing showed elevated levels of CRP and interleukin (IL)-6, and CT showed worsening pneumonia." (PMID 37124420, 2023). "Overall, during the early infection phase, AC migration led to persistent pneumonia characterized by a Th2 bias in mice (mainly IL-13 and IL-6) and rats (mainly IL-6)." (PMID 35617354, 2022). "Previous studies have also focused on the correlation between “IL-6 and IL-10 ratio” and disease severity, proving its unique clinical value in early diagnosis of severe pneumonia." (PMID 36544765, 2022). "We therefore conducted this study to assess the value of IL-6 in the diagnosis of early pneumonia after cardiac surgery and compare it with that of PCT, CRP and WBC counts." (PMID 35794529, 2022). "In particular, plasma IL-6 was significantly elevated and increased approximately 30-fold in pneumonia cases, with an average value of 43.11 pg/ml." (PMID 36119044, 2022). "ANA positivity wasn't associated with disease severity (p = 0.470), pneumonia severity (p = 0.291), outcome (p = 0.612), or markers of inflammation: CRP (p = 0.151), IL-6 (p = 0.652), ferritin (p = 0.112), SII (p = 0.722)." (PMID 36106319, 2022). "In co-infected hamsters, an involvement of IL-6 in the increased severity of pneumonia was discussed." (PMID 35632761, 2022). "The in vivo experimental results showed that rhein has a positive therapeutic effect on pneumonia, significantly reducing the concentration of pro-inflammatory factors [interleukin (IL)-6 and IL-1β] and improving lung disease." (PMID 35387347, 2022). "Out of 48 cytokines analyzed and compared between pneumonia patients who had a poor prognosis and pneumonia patients who had a good prognosis, the combined predictive value of IL-6 and G-CSF was found to be the most reliable." (PMID 35382755, 2022). "As shown from the pneumonia samples, representative proinflammatory cytokines such as IL-6, IL-1β, IL-4, IFN-γ, and TNF-α were adsorbed to the DND irrespective of the disease type." (PMID 35445003, 2022). "When compared with the healthy children, children who were infected with HMPV pneumonia had a significantly lower level of IL-2 (p < 0.001) and higher levels of IL-4 (p < 0.001), IL-6 (p = 0.001), IL-10 (p < 0.001), and IFN-γ (p < 0.001)." (PMID 36496397, 2022). "• The overexpression of cytokines (i.e., TNF-α, IL-2, IL-10, IL-1, and IL-6) leads to development lung damage, cell death, severe pneumonia, ARDS, lung fibrosis, local or systemic thrombosis and multiple organ failure." (PMID 35422702, 2022). "Laboratory abnormalities in infants with pneumonia included elevated IL-6 levels to an average of 9.1 pg/ml, and elevated D-dimer levels to an average of 608 ng/ml." (PMID 35546159, 2022). "Pneumonia cases showed increased IL-6 levels compared with pure DAD cases, whereas CRP levels were weaker discriminators." (PMID 35992303, 2022). "Activation of pro-inflammatory (M1) phenotype macrophage is a key parameter of acute pneumonia, which stimulates cytokine storm by releasing proinflammatory factors such as IL-1β, IL-6 and TNF-α." (PMID 36714100, 2022). "The disease exhibits symptoms like severe pneumonia, associated to a severe inflammatory reaction including high C-reactive protein (CRP) and interleukin-6 (IL-6) levels, low albumin and eosinophils, but high sedimentation rate and lymphopenia." (PMID 36211365, 2022). "In contrast, during the recovery period of the pneumonia group, such as for cases P1, P2, and U1, there were decreases in certain cytokines, such as IL-2, IL-6, MCP-3, and TNF-α." (PMID 36119044, 2022).
pneumonia (continued). "In accord with the critical role of uncontrolled inflammatory response in pneumonia, significantly lower expression of IL‐6 in BAL fluid of UGRP1 KO mice was observed." (PMID 35652821, 2022). "In patients with pneumonia, the IL-6, IFN-γ, G-CSF, M-CSF, IL-1Ra, IL-2Ra, IL-10, HGF, MCP-1, and MCP-3 expression levels showed a strong positive correlation." (PMID 35382755, 2022). "IL-6 is highly induced in clinical cases of pneumonic plague and is abundant in serum of severe pneumonia patients." (PMID 34780267, 2022). "A multiplex-biometric immunoassay showed that pneumonia cases had higher levels of serum cytokines (G-CSF, IL-2, IL-6, IL-10, IL-18, IP-10, MCP-3, and TNF-α) than bronchitis cases." (PMID 36119044, 2022). "Compared with the HMPV pneumonia group and healthy control group, the former had a significantly lower level of IL-2 and higher levels of IL-4, IL-6, IL-10, and IFN-γ." (PMID 36496397, 2022). "Pneumonia is accompanied by a “cytokine storm” that is characterized by sustained elevated interleukin-6 (IL)-6, activated endothelium, increased angiotensin-converting enzyme 2, and severe thromboembolic complications." (PMID 35064792, 2022). "To further evaluate the efficiency of the phages in treating pneumonia, we examined the concentrations of cytokines, including interleukin-1β (IL-1β), IL-6, and tumor necrosis factor alpha (TNF-α), and pathological injuries at 24 and 48 h postinfection." (PMID 36165773, 2022). "Studies have shown that gabexate inhibits the inflammatory expression of IL-6 and IL-10 and attenuates the inflammatory effects of influenza pneumonia." (PMID 35747501, 2022). "Additional differences were found between severe and mild pneumonia patients; those with severe pneumonia had higher IL-6 and PAB levels and lower total SH-groups." (PMID 36420478, 2022). "Pathological examinations and cellular profiles of BALF showed that H-AASD exacerbated pneumonia incidence in KP infected mice and increased expression of cytokines (IL-1β, IL-6, IL-12, IFN-γ, TNF-α) and chemokines (KC, MCP-1, MIP-1α) related to KP in BALF." (PMID 34333291, 2021). "In studies comparing postoperative serum cytokine levels in TTE and video-assisted thoracoscopic esophagectomy, patients undergoing the latter procedure had significantly lower postoperative IL-6, IL-8, and IL-10 level and postoperative pneumonia incidence." (PMID 33789620, 2021). "Previous clinical studies reported that the circulating levels of pro-inflammatory cytokines, including tumor necrosis factor-α (TNF-α), IL-6, and IL-8, are generally elevated in patients with pneumonia." (PMID 34768890, 2021). "Then, the expressions of 25-OH-VD, VDR, TGFβ, IL-2, IFN-γ, TNFα, IL-1β, Ca2+, PCT, CRP, and IL-6 in mild pneumonia, severe pneumonia, and healthy controls were determined using qRT-PCR, western blot, ELISA, and calcium colorimetry assay." (PMID 34643152, 2021). "Upon admission to the hospital, the IL-6 levels of nine patients were below 150 ng/l, indicative of local inflammation, such as happens during pneumonia." (PMID 33903660, 2021). "Significantly increased production of soluble TNF receptors, TNF-α, IL-1β and IL-6 are also observed in P. gingivalis-infected pneumonia model." (PMID 35071321, 2021). "We present the case of a 70-year-old patient hospitalized for COVID-19 related pneumonia who was treated with off-label interleukin (IL)-6 inhibitor tocilizumab and eventually developed prolonged delirium." (PMID 33777563, 2021). "Severity of pneumonia according to American Thoracic Society and Infectious Diseases Society of America (ATS/IDSA) criteria, higher values of IL-6 and lower platelet counts are risk factors for noninvasive support failure." (PMID 34830728, 2021). "We identified specific cytokine profiles in patients with severe pneumonia, which presented as high Th1 cytokines, low Th2 cytokines, high IL-6, and low other Th17 cytokines." (PMID 34692846, 2021).
pneumonia (continued). "Patients who died (n = 3) were more likely to present bilateral pneumonia (100% vs 14.3%) at diagnosis and less reduction in interleukin 6 (IL-6) at day 14, as compared to those who survived." (PMID 33747583, 2021). "A double-blinded randomized study comparing a placebo to the ticagrelor treatment in pneumonia showed that P2RY12 inhibition resulted in a significant decrease in plasma IL-6 levels." (PMID 34589424, 2021). "Upon cytokine analysis, a higher level of IL-6, IL-8, and IL-10 was detected in severe pneumonia patients." (PMID 34305892, 2021). "IL-6 is increased in COVID 19 infected patients with severe pneumonia and these higher IL-6 levels have been correlated with lower serum sodium levels in these patients." (PMID 34926496, 2021). "TCZ appeared to be a good treatment option in patients with CRS and severe and critical pneumonia, and for patients with raised IL-6 levels despite single TCZ therapy, a repeat dose is recommended." (PMID 35004038, 2021). "In general, patients with poor diagnosis (severe pneumonia or death) had specific cytokine profiles, with high Th1 cytokines and low Th2 cytokines, high IL-6, and low other Th17 cytokines." (PMID 34692846, 2021). "Modern molecular immunology believes that the inflammatory response will stimulate the liver to synthesize CRP in large amounts through factors such as IL-6, so its level will be significantly higher in children with pneumonia." (PMID 34956578, 2021). "In patients with severe pneumonia, a very high level of cytokines (IL-6, IL-8, IL-10, and TNF-α) and large subtypes of macrophages have been observed but no activation of NK cells CD8+ T cells is evident." (PMID 34305892, 2021). "Hyperproduction of pro-inflammatory cytokines such as IL-1β, IL-6, IL-12, IFN-γ and TNF-α have been linked to the pathogenesis of tissue injury observed in SARS-CoV-2 induced pneumonia seen in humans." (PMID 34929014, 2021). "Downregulation of the inflammatory factor IL-6 can treat lipopolysaccharide (LPS)-induced pneumonia effectively." (PMID 33681222, 2021). "Blood IL-6 is a useful marker in determining the severity of the lung injury and inflammatory response in children with pneumonia, with higher levels correlating with disease severity and early mortality." (PMID 34708133, 2021). "We also showed that the inflammatory cytokines such as IL-1α, IL-6, and IL-12 p40 in Mp-induced pneumonia are dependent on the TLR2 in mice." (PMID 34937175, 2021). "The salivary IL-6 level was significantly higher in children with pneumonia compared to healthy controls." (PMID 34708133, 2021). "A marked increase in IL-6 and other inflammatory cytokines during pneumonia was demonstrated in this study." (PMID 34109187, 2021). "Certainly, markers of inflammation such as CRP, IL-6, or ferritin were significantly elevated among patients with pneumonia." (PMID 34728695, 2021). "It echoes that the elevated serum IL-6 correlates with pneumonia, ARDS, and adverse clinical outcomes." (PMID 33178109, 2020). "Proinflammatory cytokines (TNF-α, IL-6 and IL-1β) are considered as major inducers of the inflammatory response and involved in systemic response and local injury during pneumonia." (PMID 33551807, 2020). "Since the levels of cytokine and chemokine in airway epithelial cells (e.g., MCP-1, IL-6, etc) have been correlated with lethal lung injury and pneumonia, we evaluated IL-6 and MCP-1 levels in BAL fluids collected on day 6 using the Quansys multiplex ELISA." (PMID 32636840, 2020). "Our results also detected increased IL-6 in the urine which was elevated in all pneumonias compared to healthy controls." (PMID 32770049, 2020). "IL-6 was the independent predictor of the severity of lung injury in COVID patients with pneumonia after controlling for confounders." (PMID 32727465, 2020). "Kidney damage can be caused by circulating inflammatory factors such as tumor necrosis factor (TNF)-α and interleukin (IL)-6, which are originated from pneumonia, happened in the lung." (PMID 33196669, 2020).